EID2B (EP300 interacting inhibitor of differentiation 2B)
Description:
Acts as a repressor of MYOD-dependent transcription, glucocorticoid receptor-dependent transcription, and muscle differentiation.
Synonyms: EID-2B; EID-3; FLJ38944
Tractability: PROTAC: ubiquitination databases record sites on it.
Gene: Protein-coding gene on chromosome 19 (39,530,987 to 39,532,852, reverse strand). Ensembl gene ENSG00000176401.
Subcellular location: Nucleus
Gene Ontology:
Molecular function: identical protein binding; protein binding; transcription corepressor activity
Biological process: negative regulation of DNA-templated transcription; negative regulation of myoblast differentiation
Cellular component: nucleus; nucleoplasm
Genetic constraint (gnomAD): Loss-of-function variants: 1 observed, 1.93 expected, observed/expected ratio (o/e) 0.52, 90% interval 0.17 to 1.76. That is too few expected variants to judge how well the gene tolerates losing a copy. Missense variants: 66 observed, 62.39 expected, observed/expected ratio (o/e) 1.06, 90% interval 0.87 to 1.3. Synonymous variants: 30 observed, 28.83 expected, observed/expected ratio (o/e) 1.04, 90% interval 0.78 to 1.41.
Homologues: Orthologues: chimpanzee EID2B (99% identical), macaque EID2B (94% identical), mouse Eid2b (52% identical). Paralogues in human: EID2 (45% identical), EID1 (25% identical).